KEAP1 (kelch like ECH associated protein 1)
Diseases named in the same sentence as KEAP1 in open-access papers (continued):
Sharing a sentence is not in itself a finding about the gene and the disease.
cancer (continued). "In the unstable oxidative microenvironment of hypoxia/reoxygenation, cancer cells also exhibit reduced Keap1 expression, which promotes nuclear translocation and increased expression of Nrf2, which, in turn, contributes to the removal of ROS and the progression of cancer." (PMID 39664581, 2024). "We found that KEAP1 expression was higher in the pan-cancer, including ALL, than in normal tissue." (PMID 37251921, 2023). "In addition, NRF2 can be controlled by epigenetic modification, for instance, the hypermethylation of CPG sites in the KEAP1 promoter is frequent and leads to the downregulation of KEAP1 in several types of cancer." (PMID 37189700, 2023). "Investigating novel molecular mechanisms, including NF-κB, Ho1, and Keap1, and developing enhanced, targeted Nrf2 activators or inhibitors to uncover the interplay among cancer, glycolipid metabolic disorder, inflammation, and neurological disorders will be upcoming trends and hotspots." (PMID 37779908, 2023). "Nrf2/Keap1 signaling is reported to be involved in cancer cell growth and survival." (PMID 38235110, 2023). "Notably, Kelch ECH-associated protein 1 (Keap1) and the speckle-type POZ protein (SPOP) are recognized as cancer-associated adaptors of CUL3, exerting pivotal roles in tumor progression." (PMID 37906282, 2023). "Therefore, the identification and discovery of new KEAP1 inhibitors represent an effective strategy for combating the threat of cancer through targeting this pathway." (PMID 37630254, 2023). "Consequently, inhibiting KEAP1 has been proposed as a potential therapeutic approach for addressing oxidative stress-related diseases such as cancer." (PMID 37630254, 2023). "Finally, we examined the expression in pan-cancer from TCGA and found that all the tumors except for the testis were of higher KEAP1 expression compared with normal tissues." (PMID 37251921, 2023). "Based on previous studies and our own results, we surmised that the ETGE motif–containing proteins might potentially bind to KEAP1 and regulate KEAP1/NRF2 signaling in cancer cells." (PMID 36719368, 2023). "NRF2/KEAP1 signaling pathway is involved in regulating oxidative stress conditions, which play a key role in inducing inflammation, endothelial disfunction and cancer." (PMID 37296999, 2023). "Moreover, several studies demonstrated that both natural and synthetic compounds can modulate NRF2/KEAP1 signaling in normal and cancer cells." (PMID 37296999, 2023). "Aberrant activation of NRF2 in cancer is attributed to gain-of-function mutations in the NRF2-encoding gene NFE2L2 or a loss of function of its suppressor, Kelch-like ECH-associated protein 1 (KEAP1)." (PMID 36765792, 2023). "The regulatory molecular mechanism of the NRF2/KEAP1 pathway against metabolic reprogramming in cancer has been recently reviewed, suggesting that regulation of the NRF2/KEAP1 axis might serve as a novel therapeutic strategy for cancer." (PMID 37375797, 2023). "Given the interaction of NFE2L2 with KEAP1 via the DLG and ETGE motifs, it was found that the prevalence of Nrf2-activating mutation (MU) was higher than that of Nrf2-inactivating mutation (MU) in the majority of cancer types." (PMID 37794491, 2023). "Sequestosome-1, which is also called p62, is a multidomain, multifunctional protein, which is involved in autophagy, defense against oxidative stress via activation of the Keap1/Nrf2 system, protein aggregation and sequestration, and apoptosis for different types of cancer cells." (PMID 36673375, 2023). "Notably, the production of ROS contributes to the cytotoxicity of cancer cells, indicating the significant role KEAP1 plays in therapeutic resistance." (PMID 37251921, 2023).
cancer (continued). "Aberrant activation of NRF2 in cancer is attributed to either gain-of-function mutations in the NRF2 encoding gene NFE2L2 or loss of function of its suppressor, Kelch-like ECH-associated protein 1 (KEAP1)." (PMID 36765792, 2023). "The long-term use of this kind of Keap1/Nrf2 inhibitors enables the accumulation of active Nrf2, which may trigger other mechanisms leading to cancer." (PMID 37175549, 2023). "In aging and some diseases, the Nrf2/Keap1 pathway is a protective factor, but may also act as a double agent in cancer." (PMID 37686132, 2023). "As a result, several cancer types have the NRF2/KEAP1 pathway as a primary target for chemotherapy." (PMID 37927596, 2023). "Importantly, they identified the small compound BPK-29 that disrupts NR0B1 complexes and impairs the anchorage-independent growth of KEAP1-mutant cancer cells." (PMID 36632216, 2023). "While it plays a protective role in normal cells by eliciting anti-oxidative enzymes and preventing malignant transformation, cancer cells often take advantage of the Keap1/Nrf2 pathway to protect themselves against the oxidative stress induced by chemotherapy and support their growth." (PMID 38247453, 2023). "Moreover, Nrf2/Keap1 signaling, which is a key signaling pathway that can enhance anti-oxidative stress capacity of cancer cells and exert anti-apoptotic effects, was also regulated by SETD6 in our study." (PMID 36604642, 2023). "In this methodology paper, we designed and experimentally validated a customized methylation panel for NGS analysis (OPERA_MET-A panel), to scan relevant CpG sites in 155 regions of 18 cancer-related genes mainly involved in the NRF2/KEAP1 pathway and immunotherapy." (PMID 36033501, 2022). "Interestingly, mutations in NRF2, KEAP1, and CUL3 were mutually exclusive, suggesting that they all follow the same mechanism to provide a growth advantage to cancer cells, i.e., hyperactivation of NRF2." (PMID 35326187, 2022). "Understanding more integrated Keap1-Nrf2 mediated tumor progression may facilitate the discovery of new anti-cancer treatment strategies." (PMID 35534896, 2022). "The Keap1-Nrf2 pathway plays a protective role in many diseases where oxidative stress is thought to play an essential role in disease onset and progression, including cancer, aging-related diseases, and inflammatory diseases." (PMID 35534896, 2022). "It has been documented that the Nrf2/ Keap1 signaling pathway may be responsible for the survival of cancer cells and induce apoptosis in cancer cells." (PMID 35524269, 2022). "KEAP1 interacted with Nrf2 in a redox-sensitive manner, whose dissociation could activate Nrf2 to transfer from cytoplasm to the nucleus, contributing to cancer progression." (PMID 35242279, 2022). "This suggests that aberrant Nrf2 regulation in cancer may be due to Keap1-independent Nrf2 regulatory pathways, or impaired Keap1-Nrf2 interactions at the protein level." (PMID 36552553, 2022). "KEAP1 methylation also has a great impact on cancer biology by regulating NRF2/KEAP1 signaling." (PMID 35754474, 2022). "Some important players in the response of cancer cells to elevated ROS levels are the nuclear factor erythroid-2 related factor 2 (NRF2) and its repressor protein Kelch-like ECH-associated protein 1 (KEAP1)." (PMID 36176767, 2022). "Somatic mutations in the KEAP1 and NRF2 genes are frequently observed in various cancers." (PMID 35326187, 2022). "However, some cancer cells, such as KEAP1-mutant NSCLC cells, are insensitive to ferroptosis due to the robust endogenous antioxidant activity." (PMID 35453395, 2022). "Therefore, targeting epigenetic regulation in NRF2/KEAP1 signaling is a potential strategy for cancer treatment." (PMID 35754474, 2022).
cancer (continued). "In Group J, 375 DEGs were identified as targets of Keap1-Restored cells and were enriched with distinct functions in cardiovascular disease, signal transduction, cell motility, cancer, immune system process, biological adhesion, metabolic process, and cellular process." (PMID 36142252, 2022). "In conclusion, the expression and activation of KEAP1 could be regarded as an effective therapeutic strategy for advanced human cancers." (PMID 35754474, 2022). "The Keap1-Nrf2 system has been reported to protect cancer cells from DNA-damage." (PMID 36203462, 2022). "Our investigations emphasize the critical roles of the KEAP1-Nrf2 system in cancers." (PMID 35453346, 2022). "In this paper, the current knowledge on the role of NRF2/KEAP1 signaling in cancer oxidative stress is presented, with a focus on how epigenetic modifications might influence cancer initiation and progression." (PMID 35754474, 2022). "Here, we reviewed phytochemical-based cancer treatments targeting miRNAs in NRF2/KEAP1 signaling." (PMID 35754474, 2022). "Therefore, it is assumed that Keap1 or Nrf2 mutations disrupt the interaction between KEAP1 and NRF2, thereby providing a strong antioxidant environment necessary for the survival of cancer cells." (PMID 35052618, 2022). "Overall we confirm that mutations in known cancer drivers accurately reproduce expected associations with both individual metabolites such as IDH1 mutations and 2‐hydroxyglutarate, and pathways such as KEAP1 mutations and glutathione metabolism." (PMID 36321551, 2022). "Thus, targeting the epigenetic modifications of NRF2/KEAP1 signaling is suggested as a feasible and promising therapeutic approach for cancer in three aspects." (PMID 35754474, 2022). "In addition, prognostic analysis based on TCGA expression data demonstrated that the KEAP1 expression level exhibits potential as a prognostic marker in several cancers." (PMID 35453346, 2022). "Aberrant NRF2/KEAP1 signaling is correlated with cancer initiation and progression." (PMID 35754474, 2022). "The fact that such carcinomas derived from Keap1β were larger than the carcinomas derived from Keap1−/− but much less than those carcinomas derived from Keap1+/+, demonstrates that Keap1 and partially Keap1β(Keap1Δ1–31) can promote the occurrence and development of tumours." (PMID 36142252, 2022). "We could also confirm that targeting NRF2 further upstream at its activator PERK is only rational if the cancer cell line carries a wildtype Keap1 gene." (PMID 33441543, 2021). "The Keap1-Nrf2 system is under investigation for the development of protein–protein interaction inhibitors that will stabilize Nrf2 for therapeutic effect in conditions of inflammation and cancer." (PMID 34758851, 2021). "Therefore, from a therapeutic perspective, KEAP1 methylation or NFE2L2 demethylation can be targeted to inhibit abnormal NRF2 expression in different cancers." (PMID 33808001, 2021). "While cancer cells may be under oxidative stress and have Nrf2 already activated, our data provide clear evidence that the MnP/Asc system oxidized Keap1 which may lead us to assume that this would activate the Nrf2 pathway." (PMID 33815656, 2021). "Activation of the Nrf2/KEAP1 signaling pathway leads to detoxification and antioxidant and anti-inflammatory effects in normal cells, but induces apoptosis in cancer cells and induces the death of cancer cells." (PMID 34067204, 2021). "However, more evidence reveals that the NRF2/KEAP1 signaling pathway is correlated with metabolic reprogramming in various cancer cells through several mechanisms." (PMID 33922165, 2021). "Furthermore, we discuss the potential strategies and therapeutic significance of NRF2/KEAP1 signaling pathway in cancer metabolism." (PMID 33922165, 2021). "Understanding more integrated NRF2/KEAP1-mediated cancer metabolism may facilitate the discovery of new anti-cancer treatment strategies through cancer metabolic reprogramming." (PMID 33922165, 2021).
cancer (continued). "However, in cancer cells, a ~40% increase in the cytosolic Keap1 protein level as a result of treatment with the compound (4d) was observed." (PMID 34358114, 2021). "Notably, blade-wise analysis of the Kelch domain points to stability as a possible target of cancer in KEAP1." (PMID 34065616, 2021). "However, after transplantation, Keap1-knockdown mouse-derived cancer cells exhibited higher tumorigenicity compared to wild-type transplanted cells from control mice." (PMID 34440648, 2021). "Since KEAP1 and NRF2 could modulate cell proliferation, it is considered a hallmark in cancer cells of the deregulation of the KEAP1/NRF2 axis." (PMID 34136401, 2021). "The abnormal expression of KEAP1 or NRF2 has been often observed in many cancer types." (PMID 33808001, 2021). "Activating mutations accumulate in some tumor types, suggesting that NRF2/KEAP1 may support an advantageous condition for cancer progression." (PMID 34440648, 2021). "Therefore, it can be said that Keap1-Nrf2 signaling pathways have different roles at different stages of cancer." (PMID 33841137, 2021). "Dysfunctional or mutant Keap1 in cancer cells leads to an accumulation of Bcl2." (PMID 34400968, 2021). "Although the roles of Keap1/Nrf2 and their downstream genes in various cancers have been widely documented, their role in regulating cell motility still remains unclear, particularly in cancer cells." (PMID 33441941, 2021). "Keap1 (Kelch-like ECH-associated protein 1) is one of the adapter proteins in the Cul3-RING ubiquitin ligase complex and is well known because the Keap1-Nrf2 pathway has cell-protecting functions against various xenobiotic and oxidative stresses that result in neurodegenerative diseases and cancers." (PMID 34202541, 2021). "In addition, the NRF2/KEAP1 axis contributes to the several metabolic processes in cancers and the production of metabolites that promote cell proliferation and survival." (PMID 33922165, 2021). "In recent years, the Keap1/Nrf2 system has attracted much interest from scientists in basic and clinical cancer research, which suggested that this system could represent a target for new therapeutic options." (PMID 33805928, 2021). "This is maybe due to increased malignancy of cancer cells, so that Keap1 down-regulation and subsequent Nrf2 induction provide conditions for cancer growth." (PMID 33652780, 2021). "However, NRF2/KEAP1 signaling pathway is dysregulated in various cancers, thus promoting tumor cell survival and metastasis." (PMID 33808001, 2021). "In addition, KRAS mutations can co-exist with other mutations in significant genes in cancer (e.g., STK11 and KEAP1) which induces tumor heterogeneity and promotes different responses to therapies." (PMID 35096591, 2021). "In summary, we employed a genetic screen and took advantage of a cellular adaptation model to define a ubiquitination-dependent mechanism for R-loop regulation by SETX, which is controlled by the opposing activities of USP11 and KEAP1 with broad applications for cancer and neurological disease." (PMID 34526504, 2021). "Biochemical studies showed that Zn(II)–curc treatment increased the NRF2 protein levels along with its targets, heme oxygenase-1 (HO-1) and p62/SQSTM1, while markedly reduced the levels of Keap1 (Kelch-like ECH-associated protein 1), the NRF2 inhibitor, in the cancer cell lines analyzed." (PMID 33669070, 2021). "Notably, mutations in KEAP1/NFE2L2 and those in EGFR exclude each other in all cancer types with high somatic mutation rates in these genes, speaking for a high functional overlap of both pathways." (PMID 33916908, 2021). "A2M mutation was related to inflammatory cascades and might facilitate cancer development by decreasing the expression of CD29 and CD44, in addition, T790M, mTOR mutation and KEAP1 loss were identified as resistance mechanisms." (PMID 33740125, 2021).
cancer (continued). "At the center of a complex regulatory network, the NRF2/KEAP1 pathway is emerging as a critical regulator of metabolism in cancer cells as its interactions with the metabolism-related pathway including the PI3K/AKT/mTOR pathway, p62 pathway, AMPK, and TCA cycle have been revealed." (PMID 33922165, 2021). "However, Nrf2 levels are high in different types of cancer induced by several mechanisms, including mutations in the NFE2L2 and KEAP1 genes or Keap1 inhibition by oncometabolites." (PMID 34206503, 2021). "In addition, abnormal KEAP1 expression has been observed in several cancers including lung, liver, pancreas, and ovarian cancers." (PMID 33808001, 2021). "The Nrf2/KEAP1 signaling pathway plays a dual role in normal and cancer cells." (PMID 34067204, 2021). "Finally we intended to examine the role of PERK in cancer cells with a functional Keap1 protein as a NRF2-repressor." (PMID 33441543, 2021). "As the previous studies, mir-141-3p could promote the proliferation and migration of cancer cells by inhibiting the expression of KEAP1 when the miR-141-3p was overexpressed in the cancer cells by miR-141-3p mimic." (PMID 34136401, 2021). "Moreover, partial or complete depletion of KEAP1 has been shown to promote cancer initiation and growth suggesting that KEAP1 can be also regarded as a tumor suppressor, similarly to NRF2." (PMID 33808001, 2021). "However, when targeting the NRF2/KEAP1 signaling pathway for the prevention and potential treatment of cancer, the dual roles of NRF2 in cancer development have to be considered." (PMID 33925605, 2021). "The Nrf2/Keap1 signalling pathway is also known to be closely related to cancers." (PMID 34959418, 2021). "The NRF2/KEAP1 pathway is a fundamental signaling cascade that controls multiple cytoprotective responses through the induction of a complex transcriptional program that ultimately renders cancer cells resistant to oxidative, metabolic and therapeutic stress." (PMID 32443774, 2020). "Given that a subset of KEAP1 mutations lead to elevated SOX9 protein levels and tumorigenesis, our findings suggest that targeting SOX9 in cancer patients bearing such mutations could be a viable stratified approach for their treatment." (PMID 33173725, 2020). "Interestingly, mutations in KEAP1 and NRF2 are mutually exclusive and rarely occurred in the same cancer cell." (PMID 32751080, 2020). "KEAP1 mutations lead to constitutively active NRF2, enhanced transcriptional induction of antioxidants, xenobiotic metabolism enzymes, drug efflux pumps, and the subsequent protection of cancer cells against chemotherapeutic drugs." (PMID 32327612, 2020). "Examination of second-generation sequencing of a large number of tumours deposited in the catalogue of somatic mutations in cancer (COSMIC) and the cancer genome atlas (TCGA) databases revealed that NFE2L2 and KEAP1 are mutated in various common cancers, including lung, head and neck, and bladder." (PMID 33276631, 2020). "Further, Nrf2 ubiquitination and the binding affinity of Nrf2 to Keap1 is reduced in cancer cells by the competition of endogenous signaling molecules, such as p62, partner and localizer of BRCA2 (PALB2), and dipeptidyl-peptidase 3 (DPP3), with Nrf2 to bind to Keap1." (PMID 33050575, 2020). "POR has previously been found to mediate iron-dependent oxidative stress-induced cell death in a variety of cancer cells, while KEAP1 may play a role in ferroptosis through inhibiting Nrf2 action since Nrf2 is a critical regulator of ferroptosis." (PMID 32788383, 2020). "Moreover, methylation of the KEAP1 promoter has been reported to induce cancer development and chemo- and radio- resistance in multiple cancer types." (PMID 32751080, 2020).